CC2D2A (coiled-coil and C2 domain containing 2A)
Description:
Component of the tectonic-like complex, a complex localized at the transition zone of primary cilia and acting as a barrier that prevents diffusion of transmembrane proteins between the cilia and plasma membranes. Required for ciliogenesis and sonic hedgehog/SHH signaling (By similarity).
Synonyms: KIAA1345; MKS6; JBTS9; COACH2; RP93
Tractability: PROTAC: ubiquitination databases record sites on it.
Gene: Protein-coding gene on chromosome 4 (15,469,865 to 15,602,097, forward strand). Ensembl gene ENSG00000048342.
Subcellular location: Cytoplasm; Cytoplasm, cytoskeleton, cilium basal body
Subcellular location (Human Protein Atlas): Connecting piece; Mid piece; Perinuclear theca; Principal piece
Pathways (Reactome):
Organelle biogenesis and maintenance: Anchoring of the basal body to the plasma membrane
Gene Ontology:
Biological process: cilium assembly; non-motile cilium assembly; protein localization to ciliary transition zone; smoothened signaling pathway
Cellular component: ciliary transition zone; cytosol; MKS complex; cytoplasm
Genetic constraint (gnomAD): Loss-of-function variants: 106 observed, 145.9 expected, observed/expected ratio (o/e) 0.73, 90% interval 0.62 to 0.85. The upper end of that interval is the gene's LOEUF score, 0.85, which puts it in group 3 of 6, group 1 being the genes least tolerant of losing a copy. Missense variants: 1,500 observed, 1,550.4 expected, observed/expected ratio (o/e) 0.97, 90% interval 0.93 to 1.01. Synonymous variants: 537 observed, 554.62 expected, observed/expected ratio (o/e) 0.97, 90% interval 0.9 to 1.04.
Gene-disease validity (ClinGen):
ClinGen rates the evidence that CC2D2A causes each of these diseases.
ciliopathy (autosomal recessive): Definitive. A genetic disorder of the cellular cilia or the cilia anchoring structures, the basal bodies, or of ciliary function.
Homologues: Orthologues: chimpanzee CC2D2A (99% identical), macaque CC2D2A (97% identical), dog CC2D2A (88% identical), rabbit CC2D2A (88% identical), pig CC2D2A (88% identical), mouse Cc2d2a (85% identical), rat Cc2d2a (85% identical), guinea pig CC2D2A (85% identical), tropical clawed frog cc2d2a (62% identical), zebrafish cc2d2a (58% identical), Drosophila melanogaster Cc2d2a (21% identical), Caenorhabditis elegans mks-6 (18% identical). Paralogues in human: CC2D2B (34% identical), CEP76 (10% identical).
Diseases named in the same sentence as CC2D2A in open-access papers:
CC2D2A is named in the same sentence as 37 diseases in open-access papers, as found by Europe PMC text mining. Sharing a sentence is not in itself a finding about the gene and the disease. The quoted sentences say what the papers report.
ciliopathy (27 papers, 2013 to 2026). "The phenotype is primarily driven by CC2D2A‐related ciliopathy, with ABCA12, DOCK6 variants, and the 14q31.3–q32.11 deletion acting as likely genetic modifiers." (PMID 41550404, 2026). "CC2D2A (coiled-coil and C2 domain containing 2A) mutations are a relatively common cause of Joubert syndrome, a ciliopathy characterized by distinctive brain malformation and developmental delay." (PMID 39135208, 2024). "Among the mutant lines in this study we found five genes which have been previously linked to human ciliopathies: B9d2, Cc2d2a, Rpgrip1l, Ift140 and Nek930." (PMID 31243271, 2019). "Among them, Tmem67, Cc2d2a and Kif7 mRNAs were linked to Joubert syndrome and Meckel Gruber syndrome, both belonging to the ciliopathy family." (PMID 30260431, 2018). "Mutation or dysregulation of Cc2d2a, Tmem67, Kif7 plus Tmem107 and Topors, are known to cause ciliopathies." (PMID 30260431, 2018). "Mks1 and Cc2d2a are both part of a large complex of proteins implicated in human ciliopathies localized to the transition zone of cilia." (PMID 27207957, 2016). "Mutations in the transition zone gene CC2D2A cause the related Joubert and Meckel syndromes, two typical ciliopathies characterized by central nervous system malformations, and result in loss of ciliary localization of multiple proteins in various models." (PMID 26485645, 2015). "Mutations in cc2d2a have been found in patients suffering from the ciliopathies Meckel and Joubert syndrome." (PMID 25741241, 2015). "Mutations in CC2D2A cause two ciliopathies, Joubert and Meckel syndromes, and result in loss of ciliary protein localization." (PMID 26485645, 2015). "In order to shed light on the function of CC2D2A we performed a dedicated ciliary yeast two-hybrid assay with different fragments of CC2D2A against a panel of 164 proteins, containing most of the ciliopathy-associated proteins." (PMID 26485645, 2015). "Furthermore, variants in Coiled-Coil and C2 Domain Containing 2A (CC2D2A) have been recognized to cause a group of genetic disorders classified as ciliopathies." (PMID 35874825, 2022). "The photoreceptor phenotype of Alms1GT/GT mice hints at involvement in the transition from vesicular to intraciliary transport, a process controlled in part by the small GTPase Rab8 and in which ciliopathy proteins including CC2D2A and BBS proteins have been implicated." (PMID 30421101, 2019). "Furthermore, TMEM-218 can be positioned genetically and hierarchically within the MKS module, likely as a peripheral component, similar to MKS-3 (Tmem67), JBTS-14 (Tmem237), and MKS-6 (Cc2d2a), which are all ciliopathy-associated." (PMID 26982032, 2016). "CC2D2A associates with a number of ciliopathy gene products at the transition zone of cilia." (PMID 25741241, 2015). "While CC2D2A and QDPR are primarily linked to ciliopathies and neurotransmitter metabolism, respectively, their potential roles in ovarian biology warrant exploration, as ciliary dysfunction is increasingly recognized as a driver of POI." (PMID 41185014, 2025). "The CC2D2A gene is essential for primary cilia formation, and its disruption has been associated with Joubert Syndrome-9 (JBTS9), a ciliopathy with typical neurodevelopmental features." (PMID 37107568, 2023). "We investigated multiple mouse models of human ciliopathies (including Tctn2, Cc2d2a, and Tmem231 mutants) and discovered that each displays hypotelorism, a narrowing of the midface." (PMID 34672258, 2021). "NINL, an important interaction partner of three ciliopathy-associated proteins (lebercilin, USH2A and CC2D2A), was previously shown to associate with this motor complex." (PMID 26485514, 2015). "In this perspective, unraveling the cell biological function of disease genes such as CC2D2A as presented in the current study is a prerequisite for the future development of pharmacological treatments for patients with ciliopathies." (PMID 26485645, 2015).
ciliopathy (continued). "Ninein-like protein (NINL) is known to associate with this motor complex and is an important interaction partner of the ciliopathy-associated proteins lebercilin, USH2A and CC2D2A." (PMID 26485514, 2015). "CC2D2A- and TMEM67-associated ID disorders are ciliopathies, and apart from its established role in chromosome cohesion, SMC3 has been recently shown to be required for Planar Cell Polarity, a process underlying cilium formation." (PMID 24204314, 2013). "Association of mutations in Exocyst components with ciliopathies, in particular JBTS, suggest that the mechanisms uncovered in this work to explain the ciliary dysfunction in cc2d2a-/- PRs might represent a more general mechanism underlying JBTS." (PMID 29281629, 2017). "Reverse genetic mutations in the CC/TZ protein CC2D2A, axoneme protein RP2, and myosin 7A result in photoreceptor degeneration in zebrafish, indicating that zebrafish are an excellent model for the study of photoreceptor diseases associated with ciliopathies." (PMID 27737822, 2016). "NINL has been previously shown to bind several other ciliopathy proteins present at the base of cilia, specifically LCA5 and USH2A, suggesting that it may play a more pivotal role in vesicular trafficking in photoreceptors than CC2D2A." (PMID 26485645, 2015).
Joubert syndrome (11 papers, 2015 to 2026). Joubert syndrome (JS) is characterized by congenital malformation of the brainstem and agenesis or hypoplasia of the cerebellar vermis leading to an abnormal respiratory pattern, nystagmus, hypotonia, ataxia, and delay in achieving motor milestones. "CC2D2A is known to be a causative gene for approximately 10% of Joubert syndrome cases and encodes a protein crucial for primary cilia formation and function, particularly in Rab8‐dependent vesicle trafficking." (PMID 41550404, 2026). "Genetic variants in CC2D2A are associated with a spectrum of different ciliopathy syndromes, including neurological diseases such as Joubert syndrome and Meckel syndrome." (PMID 39765701, 2024). "The CC2D2A (OMIM *612013) gene is one of the most common causative genes of Joubert Syndrome-9 (JBTS9; OMIM #612285)." (PMID 37107568, 2023). "In humans, mutations in AHI1 and CC2D2A cause Joubert Syndrome and both genes have been proposed as potential modifiers of CEP290." (PMID 30970040, 2019). "Genetic mutations in genes such as CC2D2A, ABCA12, and DOCK6 have been independently implicated in syndromic forms of Joubert syndrome, autosomal recessive congenital ichthyosis (ARCI), and Adams‐Oliver syndrome, respectively." (PMID 41550404, 2026).
Meckel-Gruber syndrome (9 papers, 2014 to 2024). "Only 1 case of WES in NIHK group, the results showed that the suspected pathogenic gene CC2D2A was detected, which was related to Meckel-Gruber Syndrome." (PMID 37662847, 2023). "CC2D2A is a Meckel syndrome gene and its mutation causes embryonic lethality." (PMID 30369943, 2018). "However, we also observed a trend where genes that cluster in the same ciliary compartment tended to cause a similar phenotype; e.g., mutations in the transition zone genes CC2D2A, TCTN2, TMEM237, and CEP290 almost always resulted in either Joubert or Meckel-Gruber syndrome phenotypes." (PMID 27894351, 2016).
retinal degeneration (4 papers, 2017 to 2024). Degeneration of the retina. "To determine if heterozygous mutations in other cilia genes could exacerbate retinal degeneration, we bred cep290fh297/fh297 mutants to arl13b, ahi1, and cc2d2a mutant zebrafish lines." (PMID 30970040, 2019). "Some other retina degeneration animal models such as CC2D2A, RP2, and EYS are characterized by opsin mislocalization and further photoreceptor cell loss, and these genes are associated with cilia transport." (PMID 37351277, 2023). "In this study, we evaluated the zebrafish cep290fh297/fh297 mutant in an effort to test ahi1, cc2d2a, and arl13b as potential genetic modifiers of retinal degeneration." (PMID 30970040, 2019).
developmental delay (3 papers, 2023 to 2026). "Here, we report a unique case of a child with neuro‐ichthyosis presenting with pharmacoresistant epilepsy, severe developmental delay, and ichthyosis, in whom whole exome sequencing revealed multilocus pathogenic variants including CC2D2A, ABCA12, DOCK6, and a 14q31.3–q32.11 deletion." (PMID 41550404, 2026).
Bardet-Biedl syndrome (2 papers, 2019 to 2022). A ciliopathy with multisystem involvement. "CC2D2A has been linked to a range of CNS developmental conditions linked to PC: Joubert syndrome, Meckel syndrome and mental retardation; there is also a potential link with Bardet-Biedl syndrome (BBS)." (PMID 30886591, 2019).
Anosmia (1 paper, 2023). An inability to perceive odors. "On the other hand, deletion of Cc2d2a (MKS6), a core transition zone component, in all tissues of postnatal mice results in kidney and retinal phenotypes, but does not result in anosmia." (PMID 38110903, 2023).
COVID-19 (1 paper, 2021). A disease caused by infection with severe acute respiratory syndrome coronavirus 2. "Further to which, the top two over-expressed genes of the “COVID-19-specific gene signature” are coiled-coil and C2 domain containing 2A (CC2D2A) and human homeostatic iron regulator or high FE2+ (HFE)." (PMID 33437935, 2021). "Here, we observe over-expression of CC2D2A, HFE, and ACO1 in COVID-19 infections and lower expression in non-COVID-19 previously circulating infections." (PMID 33437935, 2021).
endometriosis (1 paper, 2022). The growth of functional endometrial tissue in anatomic sites outside the uterine body. "AEBP1 and HOXB6, together with IGF-1, CYP11A1, MMP-2, CC2D2A, IER3, STX18, maybe staging markers for endometriosis." (PMID 36532015, 2022).
Hydrocephalus (1 paper, 2012). Hydrocephalus is an active distension of the ventricular system of the brain resulting from inadequate passage of CSF from its point of production within the cerebral ventricles to its point of absorption into the systemic circulation. "In humans with JSRD, hydrocephalus is a rarer finding, however recently mutations in the CC2D2A gene (whose protein product interacts with CEP290) have been associated with ventriculomegaly and hydrocephalus." (PMID 23028714, 2012).
neuroma (1 paper, 2022). A tumor that grows from a nerve or is composed of nerve cells and nerve fibers. "Using the provided data as reference enabled us to objectively diagnose CN abnormalities, such as abnormal formation of CN3 (Col4a2), neuroma of the motor portion of CN5 (Arid1b), thinning of CN7 (Rpgrip1l) and abnormal topology of CN12 (Cc2d2a)." (PMID 36438572, 2022).
orofaciodigital syndrome (1 paper, 2021). Two syndromes of oral, facial, and digital malformations. "Human CC2D2A mutations cause Meckel and Joubert syndromes, and TMEM231 mutations cause Meckel, Joubert, and Orofaciodigital syndromes." (PMID 34672258, 2021).
ovarian dysfunction (1 paper, 2025). The inability of the ovaries to function. "Ultimately, 2 overlapping genes, including WFS1 and DRD5, for the neurodevelopment and 4 ovarian dysfunction-related genes, including WFS1, CC2D2A, PROM1 and QDPR, were identified." (PMID 41185014, 2025). "Within the deleted region, four candidate genes (WFS1, CC2D2A, PROM1, and QDPR) warrant detailed discussion regarding their potential roles in ovarian dysfunction." (PMID 41185014, 2025). "Through analysis of Genecards and OMIM databases, we identified two neurodevelopmental genes DRD5 and WFS1, and four ovarian dysfunction-related genes WFS1, CC2D2A, PROM1, and QDPR, suggesting their roles in the patient’s manifestations." (PMID 41185014, 2025).
Retinal dystrophy (1 paper, 2022). Retinal dystrophy is an abnormality of the retina associated with a hereditary process. "In contrast to Cc2d2a, Talpid3 deficiency causes retinal dystrophy through a radically different mechanism." (PMID 35846153, 2022).
disorders of the nervous system (1 paper, 2024). "Several genes are associated with disorders of the nervous system and brain development (BCL11B, CDNF, ULK4, CC2D2A, KCNK2)." (PMID 39765701, 2024).
CC2D2A also shares sentences with these, for which no sentence is quoted: achromatopsia (1 paper); Anxiety (1); autosomal recessive congenital ichthyosis (1); Bardet-Biedl syndrome type 13 (1); cutis laxa (1); Dent disease (1); epilepsy (1); Fabry disease (1); FLNB-Related Spectrum Disorders (1); genetic disorders (1); Joubert syndrome 9 (1); kidney disease (1); liver fibrosis (1); Meckel syndrome, type 1 (1); Methylmalonic aciduria (1); microphthalmia (1); Nystagmus (1); Oculomotor apraxia (1); psychiatric disorder (1); retinal diseases (1); scoliosis (1); Ventriculomegaly (1).